DMD (dystrophin)
Diseases named in the same sentence as DMD in open-access papers (continued):
Sharing a sentence is not in itself a finding about the gene and the disease.
Duchenne muscular dystrophy (continued). "To confirm that the dystrophin isoforms seen in LMS resemble those seen in Duchenne muscular dystrophy (DMD) patients, we RNA sequenced muscle biopsies from six patients with DMD and observed that DMD in dystrophin-deleted LMS transcriptomes do have similar expression to muscular dystrophy patients." (PMID 34301934, 2021). "Accordingly, the lack of functional dystrophin laying at the root of Duchenne muscular dystrophy (DMD) drives sarcolemma instability." (PMID 34091693, 2021). "Duchenne muscular dystrophy (DMD) is characterized by progressive muscle weakness and wasting due to the lack of dystrophin protein." (PMID 34575143, 2021). "Duchenne muscular dystrophy (DMD) is a degenerative muscle disorder characterized by a lack of dystrophin expression in the sarcolemma of muscle fibers." (PMID 33923553, 2021). "On the contrary, mutations that disrupt the reading frame commonly result in the lack of dystrophin, leading to the most severe disease Duchenne muscular dystrophy (DMD)." (PMID 33939732, 2021). "Duchenne muscular dystrophy (DMD) is a degenerative disorder of striated and smooth muscle cells, characterized by the absence of the cytoskeletal protein dystrophin." (PMID 34017265, 2021). "Duchenne muscular dystrophy (DMD) is a lethal genetic disease characterized by progressive muscle degeneration due to lack of functional dystrophin." (PMID 34680138, 2021). "Duchenne muscular dystrophy (DMD) is a genetic disorder that results in the absence of dystrophin, a cytoskeletal protein." (PMID 34377959, 2021). "We first analyzed mdx mice, a murine model of Duchenne muscular dystrophy (DMD) lacking full length (427 kDa) dystrophin." (PMID 32982691, 2020). "Duchenne muscular dystrophy (DMD) is a severe genetic disorder characterized by the lack of functional dystrophin." (PMID 32656189, 2020). "The absence of the dystrophin protein in Duchenne muscular dystrophy (DMD) results in myofiber fragility and a plethora of downstream secondary pathologies." (PMID 32994316, 2020). "Duchenne muscular dystrophy (DMD) is a debilitating genetic disease that affects 1 in 5,000 live male births and is characterized by the lack of functional dystrophin protein, resulting in progressive lethal skeletal muscle degeneration." (PMID 33145368, 2020). "For instance, in Duchenne Muscular Dystrophy (DMD), absence of dystrophin at the sarcolemma is compensated to some extent by utrophin during early gestational stages." (PMID 31710288, 2019). "The lack of dystrophin in Duchenne muscular dystrophy (DMD) compromises the integrity and function of muscle fibers." (PMID 29879154, 2018). "Lack of the protein dystrophin results in Duchenne muscular dystrophy (DMD), a devastating hereditary childhood disease." (PMID 28785010, 2017). "The lethal X-linked Duchenne muscular dystrophy (DMD; MIM#310200) is caused by loss-of-function mutations in the DMD gene that result in the absence of the muscle protein dystrophin." (PMID 25662218, 2015). "Duchenne muscular dystrophy (DMD) is the most common inherited neuromuscular disease and is characterized by absence of the cytoskeletal protein dystrophin, muscle wasting, and fibrosis." (PMID 24695436, 2014). "Duchenne muscular dystrophy (DMD) is characterized by the absence of the cytoskeletal protein dystrophin, muscle wasting, increased transforming growth factor type beta (TGF-β) signaling, and fibrosis." (PMID 24655808, 2014). "Duchenne muscular dystrophy (DMD) is a muscle-wasting disease in which muscle is continuously damaged due to the lack of functional dystrophin 1,2." (PMID 24057032, 2013). "Duchenne muscular dystrophy (DMD) is a severe neuromuscular disorder characterized by the absence of the dystrophin protein and is the most common form of muscular dystrophy with a frequency of 1 in 3500 male births." (PMID 24349043, 2013).
Duchenne muscular dystrophy (continued). "Melanocytes of Duchenne muscular dystrophy (DMD) patients did not express dystrophin, and the ultrastructural analysis revealed typical mitochondrial alterations similar to those occurring in myoblasts from the same patients." (PMID 23169061, 2013). "The absence of dystrophin leads to Duchenne muscular dystrophy (DMD), an incurable lethal muscle disease that affects approximately 1 to 3 boys per every 10,000 male births." (PMID 22973449, 2012). "Lack of dystrophin, as in Duchenne muscular dystrophy (DMD) and its mdx murine equivalent, renders myofibres susceptible to recurrent bouts of segmental necrosis." (PMID 26082068, 2012). "In the same way, MG-132 treatment of mdx mice rescued the expression and membrane localization of dystrophin, the protein which is absent in the skeletal muscle of Duchenne muscular dystrophy (DMD) patients and mdx mice." (PMID 22046359, 2011). "The absence of dystrophin results in loss of the entire DGC from the sarcolemma and leads to Duchenne muscular dystrophy (DMD)." (PMID 21673914, 2011). "The absence of dystrophin, as seen in patients with Duchenne muscular dystrophy (DMD) and its animal equivalent the mdx mouse, leads to a significant reduction in skeletal muscle nNOS expression and in skeletal muscle blood flow." (PMID 20447567, 2009). "The absence of dystrophin in models of Duchenne muscular dystrophy (DMD) has been connected to altered ion channel properties e.g. impaired L-type Ca2+ currents." (PMID 18516256, 2008). "At the most severe end of the dystrophinopathy spectrum is Duchenne muscular dystrophy (DMD), which occurs when there is a complete absence of dystrophin." (PMID 40451248, 2025). "In Duchenne muscular dystrophy (DMD), Elevidys received accelerated approval based on micro-dystrophin expression, yet the EMBARK Phase 3 trial did not meet its primary functional endpoint, and secondary outcomes showed only modest, non-significant trends." (PMID 41567865, 2025). "Due to a strong clinical suspicion of Duchenne muscular dystrophy (DMD), first-line genetic testing was performed using multiplex ligation-dependent probe amplification (MLPA) of the DMD gene, which was negative for deletions or duplications." (PMID 41439068, 2025). "Duchenne muscular dystrophy (DMD) is a severe form of muscular dystrophy characterized primarily by progressive skeletal and cardiac muscle degeneration due to lack of dystrophin protein in muscles." (PMID 41354786, 2025). "Duchenne muscular dystrophy (DMD) is a progressive and devastating muscle disease, resulting from the absence of dystrophin." (PMID 39014470, 2024). "Duchenne’s muscular dystrophy (DMD) is recognized by an absence of dystrophin and the dystrophin–glycoprotein complex." (PMID 38893695, 2024). "Different from Duchenne Muscular Dystrophy (DMD), in which dystrophin is completely absent in muscle tissue, while in BMD, the dystrophin gene can express some protein, but not enough." (PMID 39659883, 2024). "Two studies represent a pseudo-Duchenne Muscular Dystrophy DMD model, as the lack of the dystrophin protein accounts for the pathology of DMD." (PMID 39062842, 2024). "To date, the majority of clinical trials target patients with Duchenne muscular dystrophy (DMD), a more severe allelic disorder with infantile onset and absence of muscular dystrophin." (PMID 35880500, 2022). "In murine models of Duchenne muscular dystrophy (DMD), the absence of cytoskeletal protein dystrophin in the heart leads to alterations in Ψm, mitochondrial electron transport and contractile dysfunction." (PMID 36189806, 2022). "In Duchenne Muscular dystrophy (DMD), the absence of dystrophin from skeletal muscle, triggers necrosis." (PMID 34950049, 2021). "Duchenne muscular dystrophy (DMD) is the most common form and is a genetic defect characterized by an absence of dystrophin, a protein that maintains the structure of muscle fibers." (PMID 34246310, 2021).
Duchenne muscular dystrophy (continued). "In Duchenne muscular dystrophy (DMD), lack of dystrophin increases the permeability of myofiber plasma membranes to ions and larger macromolecules, disrupting calcium signaling and leading to progressive muscle wasting." (PMID 35095541, 2021). "The relevance of NO modulatory function in the ECC has been extensively exemplified in Duchenne muscular dystrophy (DMD), a lethal genetic disease characterized by the absence of dystrophin, a large protein stabilizing the tissue structure by connecting F-actin and the extracellular matrix." (PMID 33728868, 2021). "In Duchenne Muscular Dystrophy, defective DMD gene is unable to code for the protein dystrophin, and there is no known cure for DMD." (PMID 33094378, 2020). "In patients with Duchenne muscular dystrophy (DMD), the absence of functional dystrophin leads to limb muscle weakness, followed by gradual muscle atrophy, cardiomyopathy, and premature death." (PMID 33092650, 2020). "In her work on Duchenne muscular dystrophy (DMD), a disorder that is characterized by a complete absence of dystrophin protein, gene editing is achieved using single-stranded PNAs (ssPNAs) that bind over the genetic mutation of interest." (PMID 29534473, 2018). "Duchenne Muscular Dystrophy (DMD), characterised by non-functioning dystrophin, is the most severe form of MD, with an estimated incidence of 3 in 100,000 boys." (PMID 28060911, 2017). "Duchenne muscular dystrophy (DMD) is an inherited disorder, characterized by progressive muscle degeneration, due to the absence of dystrophin." (PMID 26378780, 2015). "Duchenne muscular dystrophy (DMD) is the most common and severe form of muscular dystrophy characterized by the absence of the structural membrane protein dystrophin." (PMID 24137130, 2013). "Stem cell therapy is a potential promising approach for the treatment of muscular dystrophies such as Duchenne muscular dystrophy (DMD), in which muscle fibres degenerate due to lack of the protein dystrophin." (PMID 21408080, 2011). "In patients with Duchenne Muscular Dystrophy (DMD), the absent or diminished dystrophin leads to progressive skeletal muscle and heart failure." (PMID 20492678, 2010). "Duchenne Muscular Dystrophy (DMD) is a severe muscle degenerative disease, due to absence of dystrophin." (PMID 17712422, 2007). "Duchenne muscular dystrophy (DMD), the most common lethal muscle wasting disease, is a result of an absence of muscle dystrophin." (PMID 17428346, 2007). "Duchenne muscular dystrophy (DMD) is a severe muscle degenerative disease, which results from the absence of the cytoskeletal protein dystrophin." (PMID 17712422, 2007). "At present, Multiplex ligation-dependent probe amplification (MLPA) and exome sequencing are common gene detection methods in patients with Duchenne muscular dystrophy or Becker muscular dystrophy (DMD/BMD), but they can not cover the whole-genome sequence of the DMD gene." (PMID 37254189, 2023). "Duchenne Muscular Dystrophy (DMD) is the most common muscular dystrophy, comprising a lethal recessive genetic disease attached to the X chromosome that leads to progressive muscular degeneration due to the absence of the dystrophin protein." (PMID 36313597, 2022). "Duchenne muscular dystrophy (DMD), one of the most serious genetic childhood diseases, is characterized by progressive weakness and atrophy after repetitive cycles of degeneration and regeneration due to the lack of dystrophin." (PMID 34764884, 2021). "In Duchenne muscular dystrophy (DMD), articulation of α7β1-mediated ECM binding may compensate for the absence of the dystrophin-mediated linkage." (PMID 32184725, 2020).
Becker muscular dystrophy (416 papers, 2007 to 2026). Becker muscular dystrophy (BMD) is a neuromuscular disease characterized by progressive muscle wasting and weakness due to degeneration of skeletal, smooth and cardiac muscle. "Becker Muscular Dystrophy (BMD) is a milder variant of muscular dystrophy caused by genetic defects of the dystrophin gene and characterized by late onset and slower progression." (PMID 40422224, 2025). "In 5 couples, both partners have P/LP variants in the same AR gene (CFTR, GJB2, ATP7B, DHCR7), and in one couple, a woman has a clinically significant variant in the DMD gene linked to Becker muscular dystrophy." (PMID 41595422, 2025). "Becker muscular dystrophy (BMD) is also associated with mutations in the DMD gene, leading to a significantly milder clinical presentation compared to DMD." (PMID 40141224, 2025). "In-frame mutations that preserve partial dystrophin expression typically result in milder Becker muscular dystrophy phenotypes." (PMID 41595440, 2025). "Mutations in the DMD gene can also cause Becker muscular dystrophy (BMD), which is a milder disease with a later onset and a slower progression than DMD." (PMID 40722686, 2025). "Becker muscular dystrophy (BMD) is another X-linked recessive disorder caused by mutations in the dystrophin gene, characterized by the progressive weakness of the muscles in the legs and pelvis." (PMID 40003927, 2025). "The study of the filamentous architecture of dystrophin, particularly in the context of Becker muscular dystrophy‐associated deletions, demonstrated the ability of the BioSpring simulation engine to combine SAXS data with interactive modeling." (PMID 40249023, 2025). "Mutations in the DMD gene can also lead to Becker muscular dystrophy, a milder form of the disease characterized by later onset and slower progression compared to DMD." (PMID 39985020, 2025). "The distal rod domain, including the third hinge region (hinge 3) of dystrophin, is a hotspot for in-frame deletions that cause Becker muscular dystrophy (BMD)." (PMID 39939800, 2025). "In contrast, mutations that preserve the reading frame result in the synthesis of truncated but partially functional dystrophin, causing a milder phenotype known as Becker muscular dystrophy." (PMID 41614822, 2025). "95As a result, truncated but partially functional dystrophin is produced, potentially slowing down the disease progression and causing a milder Becker muscular dystrophy phenotype." (PMID 38325390, 2024). "Becker muscular dystrophy (BMD) is a X-linked disorder produced by mutations in the dystrophin gene causing progressive muscle weakness leading to severe disability and cardio-respiratory complications." (PMID 38336890, 2024). "Another recent study of a milder form of congenital muscular dystrophy due to dystrophin mutation, Becker muscular dystrophy (BMD), pointed to a direct circadian clock connection with muscular dystrophy." (PMID 38731986, 2024). "Mutations in the DMD gene can also cause Becker muscular dystrophy, which is a milder disease with a later onset and a slower progression than DMD." (PMID 39669562, 2024). "Intriguingly, a similar hereditary neuromuscular pathology called Becker muscular dystrophy (BMD) is caused by defective truncated dystrophin, which is only 46% of the full‐length protein." (PMID 38488469, 2024). "We also investigated a variant in DMD, an X chromosome gene for which loss of function gives rise to the male neuromuscular disorders Duchene or Becker muscular dystrophy (MIM: 310200 and 300376)." (PMID 39084224, 2024). "Although induced exon skipping does not provide a cure for DMD, targeted exon skipping reduces disease severity by inducing dystrophin isoforms typically associated with the milder allelic disorder, Becker muscular dystrophy (BMD)." (PMID 39201504, 2024).
Becker muscular dystrophy (continued). "Disrupting variants in the DMD gene are associated with Duchenne or Becker muscular dystrophy (DMD/BMD) or with hyperCKemia, all of which present very different degrees of clinical severity." (PMID 37298193, 2023). "Becker muscular dystrophy is a milder and less progressive muscular dystrophy wherein mutations in the DMD gene maintain the reading frame giving rise to an internally deleted and partially functional dystrophin protein." (PMID 38010230, 2023). "Becker muscular dystrophy (BMD) is a debilitating X‐linked muscle disease caused by in‐frame mutations of the dystrophin gene." (PMID 36628607, 2023). "Many DMD variants associated with Becker-type muscular dystrophy are missense variants and show only minor impacts with protein modeling on dystrophin protein structure and function." (PMID 36834603, 2023). "Dystrophin deficiency induced by DMD gene mutations causes the progressive disorders Duchenne and Becker muscular dystrophies." (PMID 37298068, 2023). "Becker muscular dystrophy (BMD) is a variably debilitating muscle disease caused by in-frame dystrophin mutations resulting in expression of truncated dystrophin isoforms that are often expressed at reduced levels." (PMID 37534133, 2023). "Becker muscular dystrophy (BMD) is an X‐linked disorder caused by pathogenic variants in the DMD gene that allow production of internally deleted dystrophin proteins with reduced functionality." (PMID 37127427, 2023). "The most CNVs affecting a single gene in the muscle disease cohort were detected in the DMD gene (n = 7, including manifesting females), related to X-linked Duchenne or Becker muscular dystrophy." (PMID 36781956, 2023). "A reduction in the amount or size of the dystrophin protein induces Becker muscular dystrophy (BMD), which causes symptoms that are similar to those in DMD patients but less severe." (PMID 37626915, 2023). "More than 7,000 different dystrophin mutations have been identified in patients with DMD or Becker muscular dystrophy (BMD)." (PMID 37435300, 2023). "Under natural conditions, internally shortened dystrophin proteins can be observed in patients with Becker muscular dystrophy (BMD) resulting from the in-frame mutations of the dystrophin gene." (PMID 36230926, 2022). "Studies on patient cohorts with Becker muscular dystrophy and X-linked cardiomyopathy, milder forms of muscular dystrophy, show that levels of dystrophin below 30% in the skeletal muscle are adequate to prevent the start of symptoms." (PMID 35886024, 2022). "Becker muscular dystrophy is an X-linked inherited genetic disease caused by a pathogenic variant coding for the dystrophin gene and resulting in lower but detectable dystrophin expression in muscle fibers." (PMID 36431340, 2022). "Mutations that maintain the dystrophin reading frame tend to produce a truncated, but partially functioning dystrophin protein that causes the milder form, Becker muscular dystrophy (BMD)." (PMID 34737451, 2022). "These miniaturized dystrophin proteins are inspired by naturally occurring dystrophin variants seen in patients that present with a mild form of Becker muscular dystrophy." (PMID 36372234, 2022). "This includes mutations in genes coding for dystrophin in Duchenne and Becker muscular dystrophy (respectively DMD and BMD), proteins α-, ß-, δ-, γ- and ε-sarcoglycan proteins, dystroglycan, and α-2 laminin." (PMID 36613804, 2022). "This is clearly seen if we compare the debilitating progress of DMD, which is caused by out-of-frame mutations in the DMD gene, with the benign clinical phenotype of Becker muscular dystrophy, which is caused by in-frame mutations in the DMD gene." (PMID 35563214, 2022). "Becker muscular dystrophy (BMD) is a type of muscle dystrophin deficiency caused by a mutation in the DMD gene." (PMID 36304374, 2022).